FANCI (FA complementation group I)
Diseases named in the same sentence as FANCI in open-access papers (continued):
Sharing a sentence is not in itself a finding about the gene and the disease.
cancer (continued). "Other known and possibly yet undiscovered cancer mechanisms are captured by the SKY92, including cell cycle pathways (BIRC5, TOP2A, and CENPE), cell growth and proliferation (FGFR3), DNA repair (FANCF, FANCI, POLQ), and transcription factor (STAT1)." (PMID 34448362, 2022). "We identified 99 unique FANCI variants (VAF < 1%) in 516 AUS HGSC BRCA1 and BRCA2 pathogenic variant negative cases and 4878 AUS cancer-free controls from available WES data." (PMID 34861889, 2021). "There was an increased carrier frequency of FANCI c.1813C>T in BRCA1 and BRCA2 pathogenic variant negative OC families, when including the discovery family, compared to cancer-free females (3/23, 13%; OR = 5.8; 95%CI = 1.7–19; P = 0.005)." (PMID 34861889, 2021). "OC cases and cancer-free individuals from FC and non-FC populations were investigated for carrier frequency of FANCI c.1813C>T; p.L605F, the top-ranking candidate." (PMID 34861889, 2021). "We found a frameshift mutation in RAD51C and deleterious mutations, one splicing and one frameshift, in two FANC members not previously associated with cancer risk, FANCD2 and FANCI, respectively." (PMID 29659569, 2018). "For the cancer phenotypes, the reverse genetics models were enriched in DNA repair functions (p = 2×10−5, FDR p = 0.03) (POLG/FANCI, SLX4/FANCP, XRCC1, BRCA1, FANCA, CHD1L) while the additive model showed enrichment related to chromatid segregation (p = 4×10−6, FDR p = 0.005) (KIF25, PINX1)." (PMID 24349080, 2013). "Given the critical importance of FANCI as an ATR target, the phosphorylation state of the FANCI-3SQ cluster may be an appropriate biomarker of the effectiveness of several classes of ATR kinase inhibitor currently in clinical trial for the treatment of cancer." (PMID 32117957, 2020). "The six hub genes (BIRC5, TOP2A, FANCI, NCAPG2, RAD51, and RRM2) were reported to be critical to regulate cell cycle, and their abnormal expression could lead to development and progression of cancers." (PMID 32902196, 2020). "When FANCI or FANCD2 is not properly functioning, both can lead eventually not only to cancer as emphasized herein but also to aging and many other states, including metabolic disorders." (PMID 34884777, 2021).
tumor (44 papers, 2012 to 2025). "Remarkably, changes in R-loop distribution mediated by FANCI deficiency blocked the activity of Ras signaling pathway, suppressing tumor-cell proliferation and dissemination." (PMID 38200551, 2024). "Our results showed that FANCI knockout triggered changes in R-loop distribution and that genes with R-loop changes were strikingly enriched in tumor progression–associated pathways, including Ras, HIF, and VEGF signaling pathways." (PMID 38200551, 2024). "The inspection of Sanger sequencing chromatograms from OC tumour DNA from nine carriers revealed three cases exhibiting loss of the wild-type allele and retention of the FANCI c.1813C>T allele." (PMID 36833203, 2023). "We previously reported loss of the wild-type allele in bilateral OC tumours from FANCI c.1813C>T carriers, suggesting that loss of FANCI function was an early event in tumourigenesis." (PMID 36833203, 2023). "Samples with biallelic loss of FANCC or FANCI were scored as fHRP, whereas one tumor with biallelic loss of FANCM (and intact BRCA1/2) was fHRD." (PMID 36805632, 2023). "The somatic mutational signatures characteristic of HGSC tumour cells were also present in HGSC samples harbouring FANCI c.1813C>T." (PMID 36833203, 2023). "Clinically, assessing FANCI expression in patient tissues or peripheral blood could aid in early tumor diagnosis and risk stratification." (PMID 40417238, 2025). "Moreover, the close association between FANCI expression with tumor staging and pathological grading further indicates its potential utility for monitoring tumor progression and evaluating therapeutic outcomes." (PMID 40417238, 2025). "Moreover, our analysis revealed that changes in R-loop distribution mediated by FANCI deficiency blocks the activity of the Ras signaling pathway, thereby suppressing tumor-cell proliferation and dissemination." (PMID 38200551, 2024). "Examining the somatic genetic landscape of OC tumors from FANCI c.1813C > T carriers for copy number alterations, mutational signatures, and mutations in specific genes revealed that the tumor profiles from carriers are similar to characteristics seen in HGSC cases." (PMID 39767562, 2024). "The somatic genetic landscape of OC tumours from FANCI c.1813C>T carriers was investigated for mutations in selected genes, copy number alterations, and mutational signatures, which determined that the profiles of tumours from carriers were characteristic of features exhibited by HGSC cases." (PMID 36833203, 2023). "Therefore, anti-FANCI inhibitors could be developed, which not only directly suppress cell viability and tumor metastasis, but also reactivates susceptibility to chemotherapy and immunotherapy in LIHC cells." (PMID 37324186, 2023). "Interestingly, tumour samples from a bilateral OC case predominantly exhibited the FANCI variant allele suggesting that loss of the WT allele could have been be an early event in tumour progression in this case." (PMID 34861889, 2021). "The study presents an analysis of FANCI mRNA expression levels in tumor versus normal tissues using the TCGA+GTEx dataset." (PMID 40417238, 2025). "The relationship between FANCI expression and immune cell infiltration will be evaluated via the EPIC platform, while its association with tumor mutation burden will be investigated using SangerBox 3.0." (PMID 40417238, 2025). "We examined the expression of FANCI in LIHC, and our results revealed that FANCI mRNA and protein levels were significantly higher in tumor tissues than in the corresponding non-tumor tissues." (PMID 40417238, 2025). "The box plot analysis reveals a significant upregulation of FANCI in the majority of tumor types compared to normal tissues, implicating a potential role for FANCI in tumorigenesis." (PMID 40417238, 2025). "Comparisons of FANCI expression levels between tumor and non-tumor states of LIHC reveal significantly higher expression in the tumor group." (PMID 40417238, 2025).
tumor (continued). "Subsequently, receiver operating characteristic (ROC) curves were utilized to evaluate the discriminatory power of FANCI expression levels between malignant and non-tumor tissues." (PMID 40417238, 2025). "We investigated the relationship between FANCI expression and immune cell infiltration in the tumor microenvironment (TME)." (PMID 40417238, 2025). "High levels of FANCI expression have been observed in NSCLC tumor tissues, and FANCI knockdown has been shown to inhibit cell proliferation, migration, invasion, cell cycle progression, and EMT in vitro and ex vivo." (PMID 39791716, 2024). "This independent function of FANCD2/FANCI is a crucial checkpoint for tumor cells as they disproportionately depend on the G2/M checkpoint to avoid mitotic disasters." (PMID 38443946, 2024). "When the literature data are considered, the role of FANCI seems ambiguous, as this gene has been reported to play both oncogenic and tumor suppressor roles." (PMID 39456660, 2024). "FANCI, an R-loop regulator, was upregulated in almost all TCGA tumor types, including LUAD, and its high expression correlated with poor prognosis." (PMID 38200551, 2024). "HGSC tumours from cases harbouring germline FANCI c.1813C>T exhibited features consistent with tumours from HGSC cases." (PMID 36833203, 2023). "Six upregulated and mutated tumor antigens related to NMD, and infiltration of APCs were identified in patients with BLCA, including HP1BP3, OSBPL9, SSH3, ZCCHC8, FANCI, and EIF4A2." (PMID 36761744, 2023). "The transcriptional level of FANCI in tumor cells was noticeably higher than those in the corresponding normal tissues, excluding LAML and TGCT." (PMID 37324186, 2023). "We performed a series of analyses to further explore the impact of FANCI on the tumor immune microenvironment in SKCM patients." (PMID 38077326, 2023). "FANCI expression of metastatic tumor tissues exceeded that of tumor tissues in the GSE46517 dataset and TCGA-SKCM." (PMID 38077326, 2023). "FANCI expression level was higher in non−small cell lung cancer tumor tissues, and the FANCI knockdown inhibited the progression by activating EMT in vivo and in vitro." (PMID 38077326, 2023). "We performed a somatic mutational signature analysis using WES data derived from FC OC tumour DNA from FANCI c.1813C>T carriers, using COSMIC SBS signatures as a reference." (PMID 36833203, 2023). "High expression of FANCI in LIHC is associated with a poor prognosis and contributes to tumor proliferation and metastasis." (PMID 37324186, 2023). "Although the sample size was small, there appeared to be no identifiable FANCI-specific signature from the analyses of tumours from FANCI c.1813C>T carriers." (PMID 36833203, 2023). "A comparison of FANCI expression in the normal tissues and organs to tumorous tissues was investigated to elucidate the significance of FANCI expression on tumor progression." (PMID 37324186, 2023). "Lastly, a positive correlation was observed between FANCI expression and tumor-infiltration levels of CD8+ T cells, B cells, regulatory T (Tregs), CD4+ T helper 2 (Th2), and macrophage M2 cells." (PMID 37324186, 2023). "In KPLU tumors, the overall protein abundance of the FA proteins FANCD2 and FANCI were significantly reduced compared to USP28-proficient tumor samples, demonstrating that the USP28-∆Np63 axis maintains FA expression in vivo." (PMID 34611298, 2022). "For many FA or FA-related proteins upstream of the ID complex, their variants will, to some extent, impair the monoubiquitination of FANCD2 and FANCI and thus the tumor suppressive roles of FA signaling." (PMID 34884777, 2021).
tumor (continued). "Further analysis of FANCI expression in tumors and adjacent normal tissues within the TCGA dataset corroborates these findings, with paired comparisons confirming the heightened expression of FANCI in tumor tissues." (PMID 40417238, 2025). "In light of the enrichment of antigen processing pathways identified through GSEA analysis, we speculate that dysregulation of FANCI might reduce the efficiency of tumor antigen presentation, promoting immune evasion." (PMID 40417238, 2025). "Such correlations suggest that FANCI may play a role in modulating the tumor immune microenvironment, thereby influencing immune evasion or immune response." (PMID 40417238, 2025). "These patients’ next-generation sequencing reports showed a tumor mutational burden of 7 mutations/megabase and a FANCI mutation, respectively, without other mutations in DNA-damage repair proteins." (PMID 41335461, 2025). "Correlations between FANCI expression and the pathological T stages of ACC, KIRP, LUAD, and LIHC are depicted, revealing higher expression levels in advanced stages and significant associations with tumor staging and grading." (PMID 40417238, 2025). "Regarding treatment, given FANCI’s key role in DNA damage repair within tumor cells, targeting FANCI may enhance tumor cell sensitivity to radiotherapy and chemotherapy, thereby improving treatment efficacy." (PMID 40417238, 2025). "Additionally, the SKCM-TCGA, GSE15605, and GSE114445 datasets also demonstrate a significant FANCI expression upregulation in SKCM tumor tissues." (PMID 38077326, 2023). "In these different tumour types, we also identified a spectrum of somatic variants in FANCI that were not restricted to any specific region within the gene." (PMID 36833203, 2023). "In previous studies we have also demonstrated complete or partial loss of wild-type alleles in tumour DNA from FC carriers of RAD51C c.705G>T; p.Lys235Asn, RAD51D c.620C>T; p.Ser207Leu and FANCI c.1813C>T; p.Leu605Phe also from the analyses of RRCancer biobank materials." (PMID 36969007, 2023). "Finally, this study analyzed the correlation of FANCI and tumor-infiltrating immune cells by CIBERSORT, ESTIMATE, and ssGSEA algorithms." (PMID 38077326, 2023). "Additionally, FANCI expression of metastatic tumor tissues exceeded that of tumor tissues in the GSE46517 dataset and TCGA-SKCM." (PMID 38077326, 2023). "FANCI plays a vital role in the occurrence and metastasis of various tumor types." (PMID 38077326, 2023). "Additionally, FANCI expression in liver hepatocellular carcinoma showed a positive relationship with tumor infiltration levels." (PMID 38077326, 2023). "A separate IHC analysis of tumour tissues available from eight FANCI c.1813C>T carriers revealed a range of staining intensity, consistent with the expectation that the variant encoded protein could be expressed in tumours." (PMID 34861889, 2021). "In addition, considering the close relationship between FANCI and the tumor immune microenvironment, combining FANCI inhibitors with immune checkpoint inhibitors might further enhance the efficacy of tumor immunotherapy." (PMID 40417238, 2025). "Thus, FANCI is a crucial gene facilitating tumor proliferation and metastasis." (PMID 37324186, 2023). "In different tumor grades of LIHC, FANCI promoter methylation levels were significantly reduced, with lower methylation levels observed in higher-grade tumors (p < 0.05)." (PMID 40417238, 2025).
tumor (continued). "Using an external cohort, we show that the genes influencing OS within the signatures, such as FANCI and PRC1, are upregulated in CRC tumor vs. normal tissue." (PMID 39779996, 2025). "The overexpression of FANCI, CHK1, and PLK1, as well as the overactivation of the DDR pathway, cooperate to promote the cell cycle process and the division of the tumor cells." (PMID 37324186, 2023). "We conducted IHC staining on tumor tissues in SKCM patients and normal skin tissues to further explore the mechanism of FANCI in SKCM." (PMID 38077326, 2023). "Extensive and unremarkable genome-wide CNAs were evident across tumours from FANCI c.1813C>T carriers, which was consistent with those seen for HGSC tumours." (PMID 36833203, 2023). "A total of five potential tumor antigens correlated with prognosis and infiltration of antigen-presenting cells, including AUNIP, FANCI, LASP1, PSMD8, and XPO5 were identified." (PMID 35846349, 2022). "In this study, we identified five tumor antigens (AUNIP, FANCI, LASP1, PSMD8, and XPO5) that were considered promising candidates as mRNA-based vaccines." (PMID 35846349, 2022). "Our IHC analyses showed differential FANCI protein expression, with a high proportion of HGSC tumour cells exhibiting low-to-moderate levels of protein expression." (PMID 34861889, 2021). "We performed IHC analysis of an available TMA containing cores from FFPE HGSC tumour tissues and FTE cells, a proposed tissue of origin for the HGSC subtype, staining for FANCI protein." (PMID 34861889, 2021). "FANCI is a negative regulator of Akt, thus it connects PI3K-Akt, and FA pathways which have oncogenic and tumor suppressing properties, respectively." (PMID 32271791, 2020). "Despite their critical role in the cellular ICL response and their tumor suppressor function, very little is known about the structure, function, and regulation of the FANCD2 and FANCI proteins." (PMID 24278431, 2013). "Tumours with somatic FANCI variants had a higher mutational load (p = 2.2 × 10−16) and MSI score (p = 6.8 × 10−10) compared to tumours without somatic FANCI variants." (PMID 36833203, 2023). "Six tumor antigens (HP1BP3, OSBPL9, SSH3, ZCCHC8, FANCI and EIF4A2) were correlated with the expression of NMD factors and infiltration of APCs, which may be promising candidates for mRNA vaccines." (PMID 36761744, 2023). "AUNIP, FANCI, LASP1, PSMD8, and XPO5 are putative tumor antigens for mRNA vaccine development." (PMID 35846349, 2022). "Specifically, FANCI-mediated DNA damage response may synergize with aberrant cell cycle checkpoint regulation (as indicated by GSEA-enriched pathways), allowing damaged cells to continue dividing and accelerating tumor heterogeneity and evolution." (PMID 40417238, 2025). "However, high levels of the tumor-infiltrating B cells, especially regulatory B cells (Bregs), drive tumor progression by producing immunosuppressive cytokines, such as IL10 and TGF-β, which are found to be simultaneously expressed with FANCI." (PMID 37324186, 2023). "This can be explained by the frequent identification of several alterations that point towards identical treatment recommendations (e.g., BRCA mutation, ATM underexpression, FANCI, FANCA deletion for PARP inhibitors in the same patient) but were not always all named by both tumor boards." (PMID 36274133, 2022). "Therefore, immunotherapy using mRNA vaccines targeting previously recognized tumor antigens (AUNIP, FANCI, LASP1, PSMD8, and XPO5) could induce immune cell infiltration to reinvigorate the ISI patient’s immune system." (PMID 35846349, 2022). "In our earlier studies, we discovered that a new form of FANCL protein, named FAVL, dysregulates the FA signaling in non-FA human tumor cells and acts as a tumor promoting factor by inactivating FANCD2 and FANCI/the ID complex." (PMID 34884777, 2021).